CD69 (CD69 molecule)
Diseases named in the same sentence as CD69 in open-access papers (continued):
Sharing a sentence is not in itself a finding about the gene and the disease.
meningioma (6 papers, 2013 to 2024). A generally slow growing tumor attached to the dura mater. "When T cells were cocultured with siPD‐L1‐transfected NF2‐associated meningioma cells, the expression of CD69 on both CD4+ and CD8+ T cells was partly reversed, and the capacity of CD8+ T cells to kill siPD‐L1‐transfected tumor cells was partly restored." (PMID 38828669, 2024). "Female meningioma patients have significantly more often an isolated monosomy 22, which has been found to be significantly associated with greater numbers of infiltrating macrophages, natural killer cells, and activated CD69+ lymphocytes." (PMID 36077817, 2022). "Given that our study identified CD69 as a putative serum biomarker in meningiomas, it is plausible to think that this may be caused by the increased presence of tumor growth-limiting CD69+ lymphocytes in the circulation of Grade I meningioma patients." (PMID 31649887, 2019). "Accordingly, TiMa from meningiomas with isolated monosomy 22/del(22q) showed increased expression levels of several activation-associated markers with higher percentages of CD69+ (p≤0.009 vs diploid and complex tumors) and CD63+ TiMa (p = 0.006 vs diploid cases)." (PMID 24098347, 2013). "Interestingly, this was also associated with an increased percentage of CD69+ lymphocytes among meningiomas with isolated monosomy 22/del(22q) vs both cases with diploid and complex iFISH karyotypes (p<0.05)." (PMID 24098347, 2013). "Thus, increased infiltration of meningiomas by activated lymphocytes including CD69+ subsets may be associated with immune surveillance, and elimination of tumor cells that restricts the tumor growth." (PMID 31649887, 2019). "The percentages of CD4+CD69+ and CD8+CD69+ cells were analyzed, and the results showed that when T cells were cocultured with siPD‐L1‐transfected NF2‐associated meningioma cells, the expression of CD69 on both CD4+ and CD8+ T cells was partly reduced compared with that in the siPD‐L1‐NC group." (PMID 38828669, 2024). "We interrogated the TCGA database to determine whether ITGAE (CD103) and CD69, the two genes associated with CD8+ TRM T cells, were differentially expressed between GBM and meningioma patients." (PMID 36289717, 2022). "In meningioma, an increased infiltration of CD69+ lymphocytes, along with tissue macrophages and natural killer cells has been reported, which is specifically associated with the cases carrying a distinct cytogenetic profile of isolated monosomy 22/del(22q) that shows a better prognosis." (PMID 31649887, 2019). "However, further studies are required to investigate the presence of CD69+ lymphocytes in the blood stream of the meningioma patients and its correlation with serum CD69 protein for possible clinical applications." (PMID 31649887, 2019). "Notably, tumors with isolated monosomy 22/del(22q) showed greater numbers of TiMa, NK cells and (recently)-activated CD69+ lymphocytes versus meningiomas with diploid and complex karyotypes." (PMID 24098347, 2013). "In line with this hypothesis, meningiomas with isolated monosomy 22/del(22q) also displayed a greater infiltration by NK cells and lymphocytes expressing the CD69 early-activation antigen." (PMID 24098347, 2013). "Compared to the control group, Grade I meningioma patients showed increased serum levels of amphiregulin (AREG), CCL24, CD69, prolactin, EGF, HB-EGF, caspase-3, and decreased levels of VEGFD, TGF-α, E-Selectin, BAFF, IL-12, CCL9, and GH." (PMID 31649887, 2019). "In detail, the CD8+ (but not CD4+) CD103+ CD69+ TRM subset was significantly more abundant in GBM samples than in meningioma samples used herein as a control group." (PMID 36289717, 2022). "In our analysis, cells positive for the CD8, CD103, and CD69 surface markers (which define the phenotype of the CD8+ TRM lymphocytes) were detected in the GBM sample and were counted as 15 cells in the selected area, while CD8+ TRM cells were absent from meningioma samples." (PMID 36289717, 2022).
Miscarriage (6 papers, 2017 to 2025). A pregnancy that ends at a stage in which the fetus is incapable of surviving on its own, defined as the spontaneous loss of a fetus before the 22th week of pregnancy. "Both basal and stimulated CD69 expression were higher in women who experienced miscarriage compared to those with normal pregnancies." (PMID 41041305, 2025). "Although no studies have directly examined these subsets in pregnancy-related pathologies, an increased CD69 expression on peripheral T cells has been reported in patients with a history of recurrent spontaneous miscarriage." (PMID 41041305, 2025). "The GEO database (GSE113790) for recurrent miscarriage and induced miscarriage has documented 15 differential genes related to glycosylation, and existing studies have shown that CD69 and OLR1 are related to RSA." (PMID 39062484, 2024). "We demonstrate that unexplained recurrent miscarriage is associated with significantly decreased expression of the T-cell co-receptor CD8 and tissue residency marker CD69." (PMID 28112260, 2017). "A decreased level of CD69 activation in the patients in the miscarriage cohort may therefore represent dysfunction in this important cell type." (PMID 39679612, 2025). "In line with this hypothesis, a recent study found decreased expression of the tissue residency marker CD69 on CD8+ T cell populations in women with recurrent miscarriage when compared to controls." (PMID 29455474, 2018).
preeclampsia (6 papers, 2010 to 2024). Preeclampsia is a hypertensive disorder of pregnancy that is characterized by new-onset hypertension with proteinuria presenting after 20 weeks of gestation, and depending on mild or severe forms may initially present with severe headache, visual disturbances, and hyperreflexia. "Besides a potential involvement in preterm birth, MAIT cells have also been studied in early-onset preeclampsia, where circulating MAIT cells were found to be decreased and phenotypically altered, with lowered PD-1 and increased CD69 and perforin expression." (PMID 34497611, 2021). "Although the role of activated T lymphocytes is clear in the pathogenesis of preeclampsia, previous studies have been unable to detect alterations in the ratio of CD3/CD69 cells and the rate of CD25-expressing lymphocytes in preeclampsia in comparison with healthy pregnancy." (PMID 28555090, 2017).
prostate carcinoma (6 papers, 2014 to 2023). A carcinoma that arises from epithelial cells of the prostate gland. "Others also found that CD69 deficient mice challenged with prostate carcinoma showed greatly reduced tumor growth and prolonged survival, which be due to the enhanced anti-tumor response of lymphocytes and increased lymphocytes in local." (PMID 37180581, 2023). "Apart from downregulating CD69 and CD25 expression, CuIIb also induced cell cycle arrest in S and G2/M phases in activated lymphocytes, which is in agreement with the previous study that this same agent caused a similar cell cycle arrest in human prostate cancer cells." (PMID 24587010, 2014). "Using coculture at an E:T ration of 1:2 on the prostate cancer monolayer PC3-LN3 4SFm28ζ, 4SFm28Tr and untransduced T cells were probed for phenotype and markers of activation (CD69 and PD-1) prior to and after exposure to monolayers." (PMID 34112739, 2021). "It has been reported that lost of CD69 enhanced anti-tumor immunity in CD69−/− mice, CD69−/− mice or CD69 antibody significantly inhibited RM-1 prostate carcinoma growth and metastasis." (PMID 34633989, 2021). "TIL from prostate cancer also featured a CD8+ predominance with a high percentage of CD8 + CD56+ NKT and expression of the CD69 activation marker." (PMID 25901284, 2015).
ZIKV infection (6 papers, 2018 to 2026). "Adult ZIKV infection is associated with immune activation with upregulation of cellular markers, including CD69, Ki67 and increases insoluble markers, including MCP-1, IL-2, IL-15, vascular endothelial growth factor (VEGF) and IL-10 in the first few days post-infection." (PMID 35130924, 2022). "We found that CD38, CD69, Fas Ligand, perforin, Ki67, and FcRγ expression was upregulated on NK cells during acute ZIKV infection, suggesting NK cells are activated, proliferating, and potentially cytotoxic during acute infection." (PMID 41000887, 2025). "Furthermore, ZIKV infection resulted in reduced levels of CD69, which is a phenomenon also reported for the flavivirus tick-borne encephalitis virus infection in healthy donor NK cells." (PMID 29600283, 2018). "During the acute phase of ZIKV infection, the number of specific innate and adaptive cell types temporarily increased, including intermediate CD14+CD16+ monocytes, CD69 + NK, HLA‐DR+CD38+ non‐naïve CD8+ T cells, Th1 CD4+ T cells, and Tbet+ plasma cells." (PMID 41556482, 2026). "We first evaluated markers predictive of acute ZIKV infection compared to healthy samples, which confirmed elevation of CD38, Fas Ligand, CD69, Ki67, and perforin as observed in our analysis of mean signal intensity." (PMID 41000887, 2025). "Immunophenotyping of whole-blood samples from ZIKV-infected patients revealed the presence of CD69+ CD56+ immune cells (predominantly the CD56+ NK cells), suggesting the possible priming of NK cells in ZIKV infection." (PMID 29600283, 2018). "Surprisingly, the activation marker CD69 was not increased upon ZIKV infection in this study." (PMID 29600283, 2018). "For example, uniquely in acute ZIKV infection, we observed negative correlations between the frequency of ABCs and CD4+ regulatory T cells (Tregs) (r = −0.86, p_adj = 0.002) and between CD69+ CD56dim NK cells and Helios+ Vδ2- γδ T cells (r = −0.77, p_adj = 0.03)." (PMID 35584677, 2022).
AIDS (5 papers, 2008 to 2017). A syndrome resulting from the acquired deficiency of cellular immunity caused by the human immunodeficiency virus (HIV). "The specific SNPs associated with having multiple AIDs were neuropilin 1 (NRP1, rs2666236), RGS1 (rs2816316), CD69 (rs4763879), and FUT2 (601338)." (PMID 29182645, 2017). "Elevated CSF HIV 1 RNA along with raised MCP-1 or neopterin suggest AIDS-dementia complex or HIV -1 encephalitis.Proviral HIV DNA within peripheral blood mononuclear cellsprognostic marker for ADC (AIDS-dementia complex).Monocytes showing increased expression of CD69, CD16, & TNF alpha." (PMID 21811520, 2010). "Examining the distribution and dynamics of CD69 expression in tissues, particularly in early SIV/HIV infection may provide important clues to the immune dysregulation that is associated with progression to AIDS." (PMID 22096538, 2011). "On the contrary, in these chronic SIV-infected macaques before the development of AIDS-related diarrhea, both CD4+ T cells and CD8+ T cells expressed higher immune activation markers CD69 and HLA-DR in the peripheral blood." (PMID 27708644, 2016). "Mo from AIDS patients with HAD were analyzed for expression of the activation markers HLA-DR, CD69, and the HIV co-receptor CCR5." (PMID 18575590, 2008).
Cirrhosis (5 papers, 2018 to 2025). A chronic disorder of the liver in which liver tissue becomes scarred and is partially replaced by regenerative nodules and fibrotic tissue resulting in loss of liver function. "While PD1 expression in CD4+ and CD8+ T cells was upregulated in cirrhosis, the percentage of cells expressing CD69 was significantly reduced in CD4+ T cells." (PMID 39656486, 2024). "In this study, we demonstrate that CXCR6+CD69+ CD8+ T cells are abundant in the ascites of patients with cirrhosis, exhibit a chronically activated bystander phenotype, and correlate with clinical parameters of disease severity." (PMID 38882602, 2024). "We determined that circulating MAIT cells were activated in patients with cirrhosis by the elevation of CD69 levels." (PMID 34321090, 2021). "Subsequently, we asked whether the accumulation of CXCR6+CD69+ CD8+ T cells in the ascites compared with blood could also be induced by the ascites milieu in the peritoneal cavity of patients with cirrhosis." (PMID 38882602, 2024). "The results indicate that CXCR6+CD69+ CD8+ T cells in ascites are associated with disease severity and may contribute to inflammation in patients with decompensated cirrhosis, suggesting that targeted inhibition of this immune cell subset may be a viable therapeutic option." (PMID 38882602, 2024). "Indeed, we could demonstrate that frequencies of ascites CXCR6+CD69+ CD8+ T cells correlate with markers of disease severity in patients with decompensated cirrhosis, suggesting that these cells may play an important role in the disease pathogenesis." (PMID 38882602, 2024). "Blood MAIT cells from patients with cirrhosis displayed an activated phenotype, characterized by higher frequencies of CD25+ and CD69+ MAIT cells as compared to control individuals." (PMID 29858567, 2018).
contact dermatitis (5 papers, 2016 to 2025). An inflammatory skin condition caused by direct contact between the skin and either an irritating substance or an allergen. "The S100A8/S100A9 tetramer modulates the immune response in skin granuloma and irritant contact dermatitis models by regulating the basal migration of monocytes through specific interactions with CD69." (PMID 40270593, 2025). "In an experimental model of contact dermatitis, blocking or deleting Cd69 increased tissue damage and recruitment of Th1 and Th17 lymphocytes." (PMID 37039643, 2023).
Crohn disease (5 papers, 2020 to 2026). A gastrointestinal disorder characterized by chronic inflammation involving all layers of the intestinal wall, noncaseating granulomas affecting the intestinal wall and regional lymph nodes, and transmural fibrosis. "Patients with Crohn’s disease had a significantly lower shift in CD3+CD69+ cell population and less interferon-g response than the controls." (PMID 39204303, 2024). "Hookworm antigen decreased immune reaction in patients with Crohn’s disease by lowering shift in CD3+CD69+ cell population and interferon-g response than the controls." (PMID 39204303, 2024). "CD69 antigen is expressed on T cells soon after exposure to infectious antigens and the lower change in their expression indicate a reduced exposure to hookworms in Crohn’s disease patients." (PMID 39204303, 2024). "At the same time, Tc17 cells are increased in Crohn’s disease and highlighted by expression of CD6high, CD39, CD69, PD-1, and CD27low, which can be targeted to inhibit disease." (PMID 41145211, 2026). "We were able to show that CD69+CD103+ cells with a TRM phenotype are increased in the lamina propria of patients with ulcerative colitis (UC) and Crohn’s disease (CD) and that high levels of CD4+ TRM cells in IBD patients are associated with early relapse." (PMID 33542725, 2020). "We performed flow cytometry, bulk, and single-cell RNA-sequencing to profile ileal lamina propria and intraepithelial CD4 T cells (CD4CD8αα, regulatory T cells (Tregs), CD69− and CD69high Trm T cells) in controls and Crohn’s disease (CD) patients (paired non-inflamed and inflamed)." (PMID 37565620, 2023).
dementia (5 papers, 2010 to 2025). Loss of intellectual abilities interfering with an individual's social and occupational functions. "Monocytes with increased expression of CD14 and CD69 have been reported in HIV-associated dementia and culture supernatants from the latter were shown to induce apoptosis in human brain aggregates." (PMID 24341794, 2013).
metabolic syndrome (5 papers, 2019 to 2025). A cluster of metabolic risk factors for CARDIOVASCULAR DISEASES and TYPE 2 DIABETES MELLITUS. "We further found CD4+ memory cells expressing CD69 were most strongly associated with glucose intolerance and alterations in adipocyte gene expression, providing a plausible mechanistic link to altered mature adipocyte function and development of metabolic syndrome." (PMID 37711619, 2023).
parasitemia (5 papers, 2014 to 2026). "Indeed, the subset of BCG vaccinated volunteers with early lymphocyte and monocyte activation were also those with lower parasitemia within the BCG group, and early NK cell CD69 expression and monocyte HLA-DR expression were correlated with decreased parasitemia." (PMID 30787276, 2019). "We show that the parasitemia was higher at the early stage, i.e. at days 6–7 of Plasmodium berghei ANKA infection in Ly49E KO mice, which correlated with lower induction of CD69, IFN-γ and TNF-α in DX5− liver NK cells at day 5 post-infection." (PMID 24498110, 2014). "In the absence of parasitemia, up to 3.5% of NK cells expressed CD69, therefore >3.5% CD69 expression was considered significant NK cell activation above background." (PMID 31921133, 2019).
Parkinson disease (5 papers, 2011 to 2025). A progressive degenerative disorder of the central nervous system characterized by loss of dopamine producing neurons in the substantia nigra and the presence of Lewy bodies in the substantia nigra and locus coeruleus. "At this timepoint, an early pro-inflammation was observed in vehicle-treated hαSyn Parkinson’s disease mice with elevated percentages of CD8+CD69+ T cells in brain and increased levels of interleukin-2 (IL-2) in the cervical lymph nodes and spleen." (PMID 36587195, 2022). "Postmortem immunohistochemistry of the substantia nigra (SNpc) from Parkinson's disease patients demonstrated that practically all CD8+ T cells were CD69+, with half being CD103+, indicating TRM infiltration in Parkinson's disease lesions." (PMID 41388658, 2025). "In a heterogeneous group of subjects, GrK was more abundant in brain CD103–CD69+CD8+ T cells than CD103+CD69+CD8+ cells populations, but most brain donors had no neurological disease or were patients with MS or Parkinson’s diseases and no data could be correlated with AD16." (PMID 40993111, 2025).
psoriatic arthritis (5 papers, 2019 to 2025). Joint inflammation associated with psoriasis. "In psoriatic arthritis, synovial fluid is enriched for CD69+CD103+CD8+ TRM cells that secrete IFN-γ and TNF-α and, together with IL-17A, induce cartilage-degrading enzymes, thereby directly promoting cartilage destruction." (PMID 41462958, 2025). "In the circulation, we found increased percentage of CD8+ CCR6+ T cell effectors expressing CD69 and of IL-17-producing T cells in patients with psoriatic arthritis." (PMID 31350460, 2019). "Therefore, we compared the ability of synovial fibroblasts from patients with RA, OA, and psoriatic arthritis (PsA) as well as a dermal fibroblast line (Hs27) to support T cell CD69 expression and T cell proliferation." (PMID 41055954, 2025). "In psoriatic arthritis, CD69+CD103+CD8+ TRM cells are enriched in synovial fluid and secrete high levels of IL-17A, indicating their involvement in local inflammation and disease relapse; Similarly, in autoimmune hepatitis, hepatic CD8+ TRM cell abundance correlates positively with disease severity." (PMID 41462958, 2025). "In subjects with psoriatic arthritis, increased levels of CD8+ CCR6+ T-cell effectors expressing CD69 were found in peripheral blood, and the accumulation of CXCR3+ CD8+ and CD69+T cells was also revealed in the synovial fluid of inflamed joints." (PMID 37892710, 2023). "The phenotypic charaterization of circulating T cells in patients with psoriatic arthritis enlightened, as a distinctive feature, a selective enhancement of CD8+ TEMRA expressing CD69." (PMID 31350460, 2019).